LINC01189 (long independently transcribed non-coding RNA 1189)
Synonyms: KGFLP1; FGF7P6
Gene: Long non-coding RNA gene on chromosome 9 (62,289,656 to 62,538,917, forward strand). Ensembl gene ENSG00000232827.
Gene Ontology:
Biological process: SRP-dependent cotranslational protein targeting to membrane, signal sequence recognition
Cellular component: signal recognition particle, endoplasmic reticulum targeting
Diseases named in the same sentence as LINC01189 in open-access papers:
LINC01189 is named in the same sentence as 5 diseases in open-access papers, as found by Europe PMC text mining. Sharing a sentence is not in itself a finding about the gene and the disease. The quoted sentences say what the papers report.
hepatocellular carcinoma (2 papers, 2021 to 2025). A malignant tumor that arises from hepatocytes. "LINC01189 is downregulated in chronically HCV-infected cells and in hepatocellular carcinoma." (PMID 41465470, 2025).
rheumatoid arthritis (1 paper, 2021). A chronic, systemic autoimmune disorder characterized by inflammation in the synovial membranes and articular surfaces. "A recent study indicated that LINC01189 was significantly altered in peripheral blood mononuclear cells of patients with rheumatoid arthritis, suggesting that LINC01189 may be a potential biomarker for rheumatoid arthritis." (PMID 33932142, 2021).
cancer (2 papers, 2023 to 2025). A tumor composed of atypical neoplastic, often pleomorphic cells that invade other tissues. "LINC01189 is transcribed into a 1193-bp transcript and has recently been reported in several cancers." (PMID 37865686, 2023). "Hsa-miR-155-5p was identified as a downstream target of LINC01189 in HCC, and forced expression of hsa-miR-155-5p abolished the inhibitory effects of LINC01189 on cancer cell growth." (PMID 41465470, 2025).
tumor (1 paper, 2025). "Mechanistically, LINC01189 functions as a tumor suppressor by sequestering hsa-miR-155-5p and preventing it from inhibiting anti-proliferative gene expression." (PMID 41465470, 2025). "Forced expression of LINC01189 reduces tumor cell proliferation and chemoresistance to 5-fluorouracil." (PMID 41465470, 2025).
LINC01189 also shares sentences with these, for which no sentence is quoted: gastric cancer (1 paper).